CD34 (CD34 molecule)
Diseases named in the same sentence as CD34 in open-access papers (continued):
Sharing a sentence is not in itself a finding about the gene and the disease.
skin squamous cell carcinoma (3 papers, 2017 to 2022). A carcinoma arising from the squamous cells of the epidermis. "The analysis of the vascular density of squamous cell carcinoma of the skin, using the immunohistochemical labeling of two main markers CD34 and smooth muscle actin (αSMA), shows a positive correlation between neovascularization and depth of tumor invasion." (PMID 35956111, 2022). "Previously, two highly tumorigenic T-IC populations, the CD34 levels of which differ, were identified in skin squamous cell carcinoma." (PMID 28633632, 2017).
small cell lung carcinoma (3 papers, 2012 to 2024). Small cell lung cancer (SCLC) is a highly aggressive malignant neoplasm, accounting for 10-15% of lung cancer cases, characterized byrapid growth, and early metastasis. "Additionally, the expression of CD34, a marker for hematopoietic stem and progenitor cells, has been found in small cell lung cancer." (PMID 39595659, 2024).
steatosis (3 papers, 2014 to 2025). Increased lipid within the cytoplasm of cells. "Therefore, the presence of SARS-CoV-2 in liver CD34+ cells may be associated with viral pathogenesis and/or pre-existing conditions in the patient, such as hepato-steatosis (which was the main pathological finding in liver samples)." (PMID 36842152, 2023). "However, the authors observed higher CD34 expression in the “lobules” and “fibrous septa in the lobules” of the biopsies with >66% of steatosis." (PMID 25525520, 2014). "Lobular CD34 staining was more intense in patients with isolated steatosis than in those with no MASLD (52% vs. 10%; p = 0.03)." (PMID 40486133, 2025).
thyroid tumor (3 papers, 2010 to 2023). A benign or malignant neoplasm affecting the thyroid gland. "Future studies should be performed in order to clarify the differences between angiogenic patterns in various histological types of thyroid neoplasm stained with a wide armamentarium of immunochemical substances, not only with conventional stains (CD34, CD31, F8 and so on)." (PMID 29147212, 2010). "Among the identified hub genes, AEBP1, CD34, COL12A1, ITGA2B, THBS2, and TPO exhibit lower expression levels in thyroid tumors." (PMID 37795451, 2023). "All kinds of thyroid tumors displayed high variability of endothelial PSMA expression (median score of positive tumors was 30%), which could be easily appreciated on serial sections stained with the broad endothelial markers CD31 and CD34." (PMID 28701709, 2017). "At variance, all thyroid tumors displayed endothelial expression of CD105, however no complete concordance with CD34 was noted." (PMID 28701709, 2017).
uveal melanoma (3 papers, 2016 to 2019). A melanoma derived from melanocytes of the uveal tract. "Two samples of the 16 uveal melanomas showed focal positive intraocular vascular staining for LYVE-1 and co-expression of CD31 and CD34." (PMID 30781402, 2019). "In tumour vessel channels non-endothelial cells have been found to express typical endothelial markers as seen in uveal melanoma cells which express the endothelial cell markers CD31 and CD34." (PMID 27346985, 2016).
vasculitis (3 papers, 2007 to 2022). "In contrast to adults with AAV, we have previously shown that children with active SV respond to endothelial injury by release of CD34 + CD133 + KDR+ EPCs into the circulation, possibly as an adaptive response to endothelial injury caused by vasculitis." (PMID 26475131, 2015). "The aim of this study was to report the 5-year outcomes of a randomized single-blinded noninferiority trial (Number: NCT 02089828) on peripheral blood mononuclear cells (PBMNCs) and purified CD34+ cells (PCCs) transplantation for treating angiitis-induced critical limb ischemia (AICLI)." (PMID 35313967, 2022). "It is possible that children mount an attempted adaptive response to this excessive endothelial injury, since we also observed increased circulating CD34 + CD133 + VEGFR2 + EPCs using flow cytometric analysis of peripheral blood monocytes in children with active vasculitis." (PMID 26475131, 2015). "Whilst our previous work showed that circulating CD34 + EPC numbers are well preserved, this study revealed that EPC function is significantly impaired in children with vasculitis." (PMID 26475131, 2015). "Previously, we demonstrated that children with active systemic vasculitis (SV) have higher circulating CD34 + CD133 + KDR+ endothelial progenitor cells (EPC); the function of these EPCs, and their relationship with disease activity in vasculitis remains largely unexplored." (PMID 26475131, 2015). "This prevents the false inclusion of CD34 and KDR double-positive mature endothelial cells which, as a result of vasculitis, might have detached from the vascular wall." (PMID 17764548, 2007).
X-linked adrenoleukodystrophy (3 papers, 2023 to 2024). X-linked adrenoleukodystrophy (X-ALD) is a peroxisomal disorder resulting in cerebral demyelination, axonal dysfunction in the spinal cord leading to spastic paraplegia, adrenal insufficiency and in some cases testicular insufficiency.
acute liver failure (2 papers, 2018 to 2020). Rapid deterioration of liver function causing encephalopathy and coagulopathy. "Previous reports have demonstrated the level of CD34+ HSCs and the different mobilizing factors leading to their increase in patients with HBV infection or in experimentally induced acute liver failure." (PMID 29461203, 2018).
acute pneumonia (2 papers, 2021 to 2023). "Furthermore, in acute pneumonia, which is predominantly associated with a PA pattern of enhancement, and in normal lung tissue, the corresponding histopathological correlation showed a regular alveolar vascular pattern on immunohistochemical staining with CD34 antibody." (PMID 34573943, 2021).
adenoid cystic carcinoma (2 papers, 2013 to 2015). A malignant tumor arising from the epithelial cells. "Adenoid cystic carcinomas have also been found to express hormone receptors and about a half of them stain for CD34." (PMID 26090035, 2015).
adrenal adenoma (2 papers, 2022 to 2023). "The percentage of CD34 staining area was significantly lower in ACC (4.023 ± 0.408%) when compared to both adrenocortical adenoma with Cushing syndrome (ACAc) (9.947 ± 1.431%, p < 0.01) and non-functioning adrenocortical adenoma (ACAn) (7.988 ± 1.188%, p < 0.001)." (PMID 35628389, 2022).
aortic aneurysm (2 papers, 2023 to 2025). A ruptured aneurysm located in the wall of the proximal portion of the descending aorta proceeding from the arch of the aorta. "Collectively, our data showed dynamic changes in CD34 expression and adventitial fibrosis in both human and mouse aortic aneurysms, implicating CD34+ cells in their pathogenesis." (PMID 39731355, 2025). "Herein, we observed downregulated expression of CD34 in both human and mouse aortic aneurysms and demonstrated that CD34+ cells give rise to Periostin+ myofibroblasts in AAA induced by both angiotensin II (Ang II) infusion and calcium chloride (CaCl2) adventitial application." (PMID 39731355, 2025). "However, the number of αSMA + /CD34 + cells and the fluorescence intensity were dramatically increased in full-thickness aortic aneurysms, indicating the transition of normal VSMCs into mesenchymal-like VSMCs." (PMID 37189183, 2023).
arteriosclerosis (2 papers, 2019 to 2025). A vascular disorder characterized by thickening and hardening of the walls of the arteries. "Importantly, c-Kit+ cells expressing classical SPC markers Sca-1 and CD34 were also observed within the neointima of aortic grafts, indicating a possible role of c-Kit+ SPCs in allograft-induced arteriosclerosis." (PMID 31079549, 2019).
B-cell neoplasm (2 papers, 2020 to 2025). A group of heterogeneous lymphoid tumors generally expressing one or more B-cell antigens or representing malignant transformations of B-lymphocytes. "This classification has been extended in the latest update of the WHO guidelines, in which TdT and CD34 expression are considered exclusive for precursor B-cell neoplasms, whereas surface light chain restriction generally indicates a mature phenotype." (PMID 32713346, 2020).
bladder tumor (2 papers, 2019 to 2021). "Notably, none of the CD34+ blasts from four patients with MDS showed LOH-15 and only one bladder tumor was with CN-LOH-15." (PMID 34680201, 2021).
breast angiosarcoma (2 papers, 2022 to 2024). A malignant vascular neoplasm arising from the breast. "Erythroblast transformation-specific-related gene and friend leukaemia virus integration gene 1 are emerging markers for breast angiosarcoma, demonstrating superior sensitivity and specificity compared to CD31 and CD34." (PMID 39093752, 2024). "It is confirmed as primary breast angiosarcoma by immunostaining in the tumor tissue for CD31, CD34, and FLI-1." (PMID 36555675, 2022).
breast phyllodes tumor (2 papers, 2023 to 2025). A benign, malignant, or borderline circumscribed biphasic neoplasm that arises from the breast. "Additionally, the immunohistochemical application of CD34, CD117, BCL-2, and Ki67 proves valuable in diagnosing and assessing the prognosis of breast phyllodes tumors." (PMID 40486880, 2025).
capillary hemangioma (2 papers, 2009 to 2019). A common hemangioma characterized by the presence of capillary-sized vascular channels without prominent epithelioid endothelial cells. "Immunohistochemically, splenic cord capillary hemangioma is characterized by predominance of CD8 negative, CD31 positive, CD34 positive cord capillary and with few sinuses." (PMID 31842913, 2019).
cerebral small vessel disease (2 papers, 2022 to 2024). Cerebral small vessel disease is the term currently used to pathological processes that affect the brain parenchymal circulation (arterioles, capillaries, and veins). "Some studies have shown that the relationship between CD34+CD133+ EPCs and cerebral small vessel disease (CSVD) is positive, but another one shows a negative relationship." (PMID 38854406, 2024). "Vascular damage progression correlated with EPC count just as a decreased amount of CD34-positive but increased amount of CD34+CD133+CD309+ and CD34+CD133+ cells suggested the progression of cerebral small vessel disease." (PMID 35626716, 2022).
chondroma (2 papers, 2022 to 2023). A benign well circumscribed neoplasm of hyaline cartilage arising from bone or soft tissue. "Compared with chondrosarcoma, chondroma is more differentiated and less likely to have binucleated cells; chordoma is more likely to immunohistochemically express CK and EMA; chondromyxoid fibroma is positive for S100, and positive to desmin and CD34 to varying degrees." (PMID 37669996, 2023). "On histopathological examination, the tumor was diagnosed as chondroma; Vimentin, S-100 and Ki-67(2%) stained positive, but EMA, CK, CK18, CD34, SOX-9 and GFAP stained negative by ICH." (PMID 35692788, 2022). "The pathological diagnosis was chondroma; ICH showed Vimentin and S-100 stain was positive, but Ki-67, CK, CK18, EMA, CD34 and GFAP stain was negative." (PMID 35692788, 2022). "On histopathological examination, the tumor was diagnosed as chondroma; Vimentin, Ki-67 (6%), SOX-9, and S-100 stained positive, but CK, CK18, EMA, CD34 and GFAP stained negative." (PMID 35692788, 2022).
chronic liver failure (2 papers, 2013 to 2022). Liver failure that develops slowly and gradually for some time, possibly for years, often as the result of cirrhosis, or malnutrition. "In patients with decompensated ALD with ASH, increased levels of circulating CD34+ cells were associated with proliferating HPC within days of G-CSF, and survival at 2 months was significantly improved in patients with acute-on-chronic liver failure." (PMID 23341981, 2013).
clear cell renal cell carcinoma (2 papers, 2013 to 2020). "The CD34 labeled vessels tended to increase with S1P1 inhibition, but the combined inhibition of S1P1 and VEGF pathways reduced blood flow in tumor, increased tumor cell apoptosis, and inhibited the tumor CD34 positive vessels in clear cell renal cell carcinoma tumor models." (PMID 32850858, 2020). "In addition, PEComa is readily differentiated from epithelioid extra-GIST and metastatic clear-cell renal cell carcinoma by positive immunohistochemical staining for Melan-A and HMB-45 and negative staining for both CD117, Dog-1, CD34 and pan-cytokeratin (AE1/AE3)." (PMID 23587410, 2013).
co-infection (2 papers, 2018 to 2025). "Additionally, the ts SeV-Cas9 vector does not stimulate an IFN response, which made the co-infection with HCMV possible and allowed for editing of CCR5 in primary cells like monocytes and CD34+ HSCs." (PMID 40663463, 2025).
complication (2 papers, 2013 to 2014). Any disease or disorder that occurs during the course of, or because of, another disease, treatment, or procedure. "CD34+ cells isolated from diabetic individuals with vascular complications show reduced NO bioavailability, and this decrease in NO is associated with reduced migration that can be corrected through exposure to NO donors." (PMID 24223881, 2013).
coronary stenosis (2 papers, 2014 to 2017). Narrowing of the coronary artery lumen diameter. "It has been shown previously that the percentage of apoptotic CD34+ progenitor cells is significantly increased in patients with ACS as compared to healthy subjects and is associated with the extent of coronary stenosis by angiography." (PMID 28060837, 2017). "Another study also reported higher levels of CD34+/KDR+ EPCs and CD34+/CD133+ EPCs in patients with severe angiographic coronary stenosis compared with those with normal coronary arteries." (PMID 24736282, 2014).
coxarthrosis (2 papers, 2024 to 2025). "The intra-articular administration of PBHSCs CD34+ targets the underlying mechanisms of coxarthrosis by promoting tissue repair and reducing inflammation." (PMID 40283486, 2025). "The study introduces a novel approach to treating coxarthrosis through intra-articular administration of PBHSCs with CD34+ markers." (PMID 40283486, 2025). "Therefore, the goal of this study was to assess and analyze the effectiveness of the implemented treatment modality and improvement in health-related quality of life in patients with coxarthrosis after intra-articular administration of PBHSCs CD34+." (PMID 40283486, 2025). "However, despite promising preliminary findings, the clinical application of CD34+ stem cells for coxarthrosis remains underexplored, with a need for standardized treatment protocols and long-term efficacy data." (PMID 40283486, 2025). "A limitation of the study is the lack of a control group without CD34+ stem cell treatment for hip osteoarthritis." (PMID 39728039, 2024).
Crohn disease (2 papers, 2017 to 2023). A gastrointestinal disorder characterized by chronic inflammation involving all layers of the intestinal wall, noncaseating granulomas affecting the intestinal wall and regional lymph nodes, and transmural fibrosis. "The expression of CD34 and platelet-derived growth factor receptor α (PDGFRα) in patients with Crohn’s disease is significantly increased in intestinal TCs that function to maintain the intestinal homeostasis." (PMID 37051017, 2023).
Cushing syndrome (2 papers, 2022). Cushing's syndrome (CS) encompasses a group of hormonal disorders caused by prolonged and high exposure levels to glucocorticoids that can be of either endogenous (adrenal cortex production) or exogenous (iatrogenic) origin. "In the present study, we investigated the in vivo effects of GCs on apoptosis in CD34+ cells enriched in HSPCs collected from patients with newly diagnosed Cushing’s Syndrome, either central CS or adrenal CS." (PMID 36555435, 2022). "The expression of the proteins involved in angiogenesis, namely CD34, VEGF, VEGF-R2, Ang1, Ang2, Tie1 and Tie2, was assessed by immunohistochemistry in ACC (n = 22), ACA with Cushing syndrome (n = 8) and non-functioning ACA (n = 13)." (PMID 35628389, 2022).
cutaneous melanoma (2 papers, 2015 to 2021). A primary melanoma arising from atypical melanocytes in the skin. "Breza and Margo also reported another case of primary cutaneous melanoma with strong expression of CD34 and S-100 and focal positivity for Melan-A and HMB-45." (PMID 34449584, 2021). "To characterize the microenvironment of SLN draining cutaneous melanoma, we have investigated the densities of macrophages and CD34+ endothelial cells and counted cytotoxic NK cells, GrzB+ cells, and CD8+ T cells." (PMID 26218530, 2015).
cystinosis (2 papers, 2021 to 2023). Cystinosis is a metabolic disease characterized by an accumulation of cystine inside the lysosomes, causing damage in different organs and tissues, particularly in the kidneys and eyes. "Our IND was cleared by the FDA on 19 December 2018, to proceed to the clinical trial using CD34+ HSPCs from the G-CSF/plerixafor-mobilized peripheral blood stem cells of patients with cystinosis, modified by ex vivo transduction using the pCCL-CTNS vector (investigational product name: CTNS-RD-04)." (PMID 34943781, 2021). "CTNS-RD-04 consists of CD34+ enriched HSPCs that underwent ex vivo transduction using the pCCL-CTNS that carries the full-sequence, human cystinosis gene (CTNS) cDNA." (PMID 34943781, 2021).
diabetic foot ulcer (2 papers, 2023 to 2024). "A recent clinical trial showed that the local administration of human peripheral blood CD34+ cells promoted the healing of diabetic foot ulcers." (PMID 38377120, 2024). "Subclustering of fibroblast subpopulations in diabetic foot ulcer samples revealed that 3 out of 10 fibroblast subclusters were consistently CD34-positive." (PMID 37904253, 2023).